DKK1 (dickkopf Wnt signaling pathway inhibitor 1)
Diseases named in the same sentence as DKK1 in open-access papers (continued):
Sharing a sentence is not in itself a finding about the gene and the disease.
tumor (continued). "Thus, DKK-1 is a biomarker for the diagnosis of aggressive HCC and a potential therapeutic target to inhibit tumor growth." (PMID 35269944, 2022). "DKK1 is an inhibitor of the Wnt signaling pathway, which can regulate Wnt through negative feedback and participates in tumor cell proliferation, apoptosis, migration, and angiogenesis." (PMID 35967426, 2022). "As DKK-1 expression correlated positively with that of AFP in tumors and is involved in angiogenesis in the tumor microenvironment, serum AFP may be a surrogate marker of DKK-1, which facilitates angiogenesis in HCC." (PMID 35269944, 2022). "We show serum DKK1 and BCMA as possible correlates of tumour burden, and that serum sclerostin may correlate with bone mineral density." (PMID 36612090, 2022). "DKK1 overexpression in MDA-MB-231 BCCs led to an increase in osteoclasts via the downregulation of Wnt signaling within osteoblasts, resulting in significantly increased osteolysis with enhanced tumor proliferation in vivo." (PMID 36497192, 2022). "In the high-CD8+ TIL BTC group, the tumor expression of β-catenin and DKK1 had a significant negative impact on either OS or RFS." (PMID 35121803, 2022). "After 4 weeks, orthotopically injected MDA-MB-231-shCONT cells spontaneously formed pulmonary metastasis, in contrast, DKK1 depletion potently decreased the metastatic burden without significantly affecting the growth of the primary tumor." (PMID 35296660, 2022). "Aldh1a1 is a marker for a cancer stem cell or tumour initiator phenotype and it is possible that elevated Aldh1a1 expression is a sign that Dkk-1 has the capacity to induce this in all or a subset of MOSJ-Dkk-1 cells." (PMID 35277659, 2022). "Our findings suggested that DKK1 might serve as a marker of prognosis for certain cancers by affecting the WNT signaling pathway and tumor immune microenvironment." (PMID 34899842, 2021). "DKK1 contributed to MDSC accumulation and tumor progression in vivo by reducing β-catenin levels." (PMID 34093545, 2021). "Naïve MSCs can inhibit Wnt signalling pathways through modulating the Dickkopf-related protein 1 (DKK1) released by tumor cells, and subsequently downregulating c-Myc and Cyclin D2 and upregulated expression of P21CIP1 and P27KIP1, leading to tumor cells suppression." (PMID 33685452, 2021). "The algorithm performed well for both sensitivity and specificity by accurately identifying tumor cells and correctly classifying tumor cells as positive or negative for DKK1 signal." (PMID 33972574, 2021). "The correlation between the ratios of tumor lesions stained with DKK1 and FOXM1 was confirmed, namely an ESCC tumor lesion which highly expressed DKK1 was also positive for FOXM1, and a tumor lesion which did not express DKK1 was negative for FOXM1." (PMID 34117362, 2021). "We identified DKK1 as the direct downstream of ZBTB38, which could mediate the tumor-suppressing function." (PMID 34697293, 2021). "The result implied that the reactivation of β-catenin-dependent Wnt signaling, in a way that suppressed DKK1, could contribute to the elimination of LCC cells and thereby prevent tumor metastasis." (PMID 34093545, 2021). "DKK1- or FOXM1-positive cells were only minimally detected in the non-tumor epithelium, whereas tumor lesions showed clear staining for DKK1 and FOXM1." (PMID 34117362, 2021). "We believe this is a reflection of the inherent challenges of measuring DKK1 expression by qPCR from FFPE tumor resections and not a reflection of the assay." (PMID 33972574, 2021). "Results of the analysis indicated DKK1 may induce MDSC accumulation and T cell dispersal during tumor progression." (PMID 34093545, 2021). "The algorithm was able to successfully identify tumor cells from non-tumor cells and categorize cells as either positive or negative for DKK1 signal, thereby passing sensitivity and specificity." (PMID 33972574, 2021).
tumor (continued). "Indeed, S2-CP8 cells and HPAF-II cells express β-catenin in the nucleus and cytoplasm, and ~80% of PDAC cases positive for both DKK1 and FOXM1 express β-catenin in the same tumor legions." (PMID 34117362, 2021). "Nonclinical models have demonstrated that DKK1 can promote tumor growth, stimulate angiogenesis, facilitate metastasis, and favor an immunosuppressive tumor microenvironment." (PMID 33972574, 2021). "In our study, we found hundreds of genes with a difference in expression by more than twofold after HELLS knockdown in the three PC cell lines; among them, 23 genes differed among the cell lines, including several tumor suppressor genes, such as TGFBR3, BTG2, and DKK1." (PMID 33280236, 2021). "Three major soluble factors were affected in the absence of CD276 on tumor cells: Dickkopf-related protein 1 (DKK-1), PAI-1, urokinase-type plasminogen activator receptor (uPAR)." (PMID 34290311, 2021). "The acidosis-related signature is composed of seven key genes (ARNTL2, DKK1, CEP55, CTSV, MYEOV, DSG2, and GBP2), all of which have elevated expression levels in PC tumor tissues compared with normal tissues and are all related to adverse clinical outcomes in patients with PC." (PMID 34993253, 2021). "DKK1, also named as DKK-1(dickkopf WNT signaling pathway inhibitor 1), has been proved to be differential expression in various tumors and participate in the regulation of growth, invasion, angiogenesis and metastasis of tumor." (PMID 33287749, 2020). "When tumours metastasised to bone (but not lung or brain), patients with higher tumour expression of DKK1 had a better outcome than patients whose tumours expressed lower levels of DKK1 (p = 0.01, log rank test of a Cox-proportional hazards model)." (PMID 31676788, 2019). "Dickkopf1 (DKK1), the specific inhibitor of Wnt/β-catenin-signaling pathway was used to investigate whether CCL14 inhibits the proliferation of tumor cells via Wnt/β-catenin pathway." (PMID 31641099, 2019). "Both of DKK1 and AREG may play significant roles in tumor progression and may offer promising therapeutic targets in HCC patients." (PMID 31649806, 2019). "Our results indicate that high DKK1 expression regardless of ß-catenin positivity is a crucial prognostic factor for predicting tumor recurrence and survival in patients with resected AGC." (PMID 29720122, 2018). "In contrast with previous results, the expression of Sost and Dkk1 decreased in osteocytes isolated from tumor–bearing mice compared to naive non-tumor–bearing mice." (PMID 30410490, 2018). "Elevated ERCC1 (HR = 2.1, 95% CI: 1.1–3.9), DKK1, CXCL12, long non-coding RNA MALAT-1 (OR = 3.65, 95% CI: 1.86–7.18) in tissue sample, and detection of circulating tumor cells (pooled HR: 2.36, 95% CI 1.41–3.96) in peripheral blood were risky factors for patients survival." (PMID 29340021, 2017). "AXIN2+DKK1 methylation significantly predicted recurrence independent of age, sex, tumor size, localization, differentiation, CIMP, BRAF and KRAS mutations." (PMID 28368388, 2017). "In addition to LATS2, many other tumor suppressors such as PPP6C, DKK1, TNFAIP1 and TP53INP1 are also verified as direct targets of miR-373, implying that miR-373 promotes cell proliferation and tumor growth under certain conditions." (PMID 25990556, 2015). "Moreover, co-expression of nuclear DKK-1 and cytoplasmic ALDH1A1 was demonstrated in the same tumor cells." (PMID 25788273, 2015). "Because improved vascular functionality is the aim of tumor vessel normalization approaches, DKK1 and DKK2 effects on angiogenesis and vessel functionality that regulates tumor hypoxia might be purposefully exploited in developing novel cancer treatments." (PMID 24091497, 2014). "We hypothesized that DKK1 and DKK2 effects on tumor growth may be due to altered tumor angiogenesis." (PMID 24091497, 2014).
tumor (continued). "Unlike DKK1, beta-catenin staining in tumor blood vessels of DKK2 Tg mice was significantly increased compared to wild-type." (PMID 24091497, 2014). "Opposite to DKK1, DKK2 enhances pericyte and SMC coverage of B16F10 tumor vessels." (PMID 24091497, 2014). "We found that 37 cases showed high DKK1 level, in which the β-catenin–negative and –positive tumor frequencies were 24.3% (9/37) and 75.7% (28/37), respectively." (PMID 25144498, 2014). "Assessment of primary tissue revealed an overexpression of DKK-1 in ER-negative breast cancer cases, but the expression appears independent of tumor grade or stage." (PMID 24528599, 2014). "Accumulated evidence has illuminated that DKK1 performs as an oncogenic factor rather than a tumor-suppressor in many tumors." (PMID 25144498, 2014). "Although most of these studies demonstrated an inhibitory role of DKK1 on tumor growth, the effect of DKK1 on vessel invasion into tumors, which is essential to tumor growth and metastasis, has not been intensively studied." (PMID 24091497, 2014). "DKK-1 serum levels did not correlate with the DKK-1 tissue scores in the cancer tissue or adjacent non-tumour tissue." (PMID 25182503, 2014). "For example, DKK1, HTATIP2, HBP1, MXI1 and CASP7, all bound by RBM47 and upregulated upon RBM47 reintroduction, have known tumor suppressive functions." (PMID 24898756, 2014). "That DKK2, but not DKK1, activates tumor angiogenesis is supported by the observation that DKK2 enhances retinal angiogenesis and induces neovessel formation in several ex vivo assays." (PMID 24091497, 2014). "The data suggest that moderate DKK1 concentrations were sufficient to inhibit MS and therefore stem cell-like activity in both ER+ve and ER−ve tumours whilst not affecting the activity within normal breast tissue." (PMID 23861811, 2013). "All these findings indicated that DKK1 performs as an oncogenic factor rather than a tumor-suppressor in HCC." (PMID 24325363, 2013). "This suggests that DKK-1 does not so much interfere with the action of Wnt 5a on the recipient tumor cells, but with its production in MΦ." (PMID 24185202, 2013). "Our present data suggest that DKK-1 exerts its main effect not on the tumor cells but on MΦ where it blocks the shift to a Wnt 5a-positive proinvasive phenotype as well as the production of Wnt 5a-carrying particles." (PMID 24185202, 2013). "Since both DKK1 and sFRP2 are established targets of TCF/β-catenin-mediated transcription, these findings suggests the presence of a negative feedback loop in MM in which DKK1 and sFRP2 act as potential tumor suppressors." (PMID 22363428, 2012). "Previous studies have shown that promoter hypermethylation causes DKK-1 silencing in CRC and that this is not an early event but more closely associated with late tumor progression." (PMID 21317455, 2010). "For example, several studies have indicated that DKK1-mediated tumor suppression is independent of canonical Wnt/β–catenin signaling." (PMID 19247449, 2009). "In extraosseous tumours, cells in contact with malignant cells did not expressed DKK1, MCSF, cathepsin K and IL6." (PMID 18253114, 2008). "Data regarding DKK-1 expression in CaP are scant: some authors report an increase DKK-1 expression in osteolytic lesions, but not in the primary tumours." (PMID 18978943, 2008). "Both models exhibited the same immunohistochemical labelling pattern: tumour cells never exhibited significant labelling for M-CSF, Dkk-1, RANKL, IL-6 or cathepsin K." (PMID 18253114, 2008). "On the basis of these observations, we hypothesised that the expression of Dkk-1 and RANKL at the periphery of the tumour was necessary for osteogenic remodelling as the tumour expands." (PMID 17987039, 2007). "In cancer, DKK1 expression does not apparently alter cell growth, especially since we noted its expression in tumours with poor prognosis." (PMID 17245340, 2007).
tumor (continued). "Hence, it seems that inhibiting DKK1 improves CD8+ T cell functioning, which could lead to better anti-tumor immune responses and make DKK1 a suitable target for CRC immunotherapy." (PMID 39788945, 2025). "However, in vivo, DKK1 overexpression significantly increased tumor engraftment in the lung, but did not affect tumor growth of the subcutaneously implanted cancer cells." (PMID 40025612, 2025). "However, these anti-tumor results were evident in cancer cells expressing both DKK1 and CKAP4 and not only CKAP4, or neither DKK1 nor CKAP4." (PMID 41149482, 2025). "Additionally, we confirmed that the tumor reducing effect of DKN-01 is due to specific inhibition of DKK1, as DKN-01 did not decrease tumor volume of HCC827-GR-shDKK1 + MRC-5 tumors." (PMID 40025612, 2025). "In support of this hypothesis, NK cells are not found in close contact with the target tumor cells when exposed to DKK1." (PMID 39885132, 2025). "As expected, DKK1 was also detected in the 4T1 tumor cells, but not in the PyMT cancer cells." (PMID 39885132, 2025). "Furthermore, CKAP4′s interaction with DKK1 is shown to play a significant role in ESCC cell proliferation and tumor formation via protein kinase B (Akt) phosphorylation, while the presence of both molecules is the necessary condition for their mechanism of action." (PMID 41149482, 2025). "To determine whether DKK1 directly affects NK cell functionality, we performed ex vivo killing assays to quantify NK cell-mediated killing of PyMT tumor cells in the presence and absence of rDKK1." (PMID 38659818, 2024). "However, only a few reports describing DKK1 expression in fibroblasts themselves have been found for non‐neoplastic diseases." (PMID 38334454, 2024). "Furthermore, mDKN01 treatment significantly reduced tumor growth in mice depleted of T cells to levels comparable to mDKN01 as single agent, suggesting that T cells are not targeted by DKK1." (PMID 38659818, 2024). "To assess whether DKK1 exerts direct effects on tumor cell proliferation, we cultured the PyMT, 4T1, and EO771 tumor cells in the presence of recombinant DKK1 (rDKK1) at various concentrations (0, 50, 100, and 200 ng/ml) for 24, 48, and 72 hours and performed an MTT assay." (PMID 38659818, 2024). "In addition to regions exhibiting fetal tumor characteristics, we also identified areas with embryonal tumor features in this tissue, characterized by high levels of WNT target genes such as NOTUM, DKK1/4, NKD1, APCDD1." (PMID 39567475, 2024). "However, regardless of the treatment with CDDP, DKK1 knockdown further contributed to higher inhibition of tumor growth." (PMID 37835450, 2023). "Since it has been reported that DKK-1 stimulated tumor growth by switching the WNT pathway from canonical to non-canonical WNT/JNK signaling, we next determined whether JNK was upregulated in Probasco + DKK-1 cells." (PMID 38067123, 2023). "Taken together, these results suggest that confluent BM-MSCs predominantly exert anti-tumorigenic activity, which might be mediated by the secretion of DKK-1 and/or TRAIL, previoulsy shown to inhibit Wnt signaling, block tumor growth, and induce apoptosis in a variety of tumor cells." (PMID 37681882, 2023). "The in vitro assays, however, do not take into account potential sources of Dkk-1, Aldh1a1 or other stress response agents derived from the tumour stroma which may not be targeted by DkkMo." (PMID 35277659, 2022). "The commonly used tumor markers in clinical diagnosis of ESCC include carcinoembryonic antigen (CEA), carbohydrate antigen 19-9 (CA19-9), cytokeratin 19 fragment (CYFRA21-1), neuron specific enolase (NSE), squamous cell carcinoma antigen (SCC), Dickkopf-related protein 1 (DKK1) and so on." (PMID 36611908, 2022). "Nevertheless, targeting DKK1 did not eradicate tumor cells completely." (PMID 35296660, 2022).
tumor (continued). "Moreover, the anti-DKK1 blocking antibody DKN-01 can reduce tumor burden in the PC-3 AR/NE negative xenograft model, and the therapeutic benefit was dependent on the presence of NK cells." (PMID 35204808, 2022). "Taken together with the results of our immunohistochemical studies, which shows that around 70% of DKK1/FOXM1 double positive ESCC tumors are negative for β-catenin in the same tumor lesions, these results suggest that FOXM1 mainly controls DKK1 expression in ESCC." (PMID 34117362, 2021). "Dickkopf-1 (DKK1) is a 266–amino acid (35-kDa) secreted glycoprotein that is expressed in a variety of human tumors, including the pancreas, stomach, liver, bile duct, breast, cervix, esophageal, and prostate and plays a functional role in human HCC cell migration, invasion, and tumor growth." (PMID 32923383, 2020). "The example of DKK1, that has been exploited as therapeutic target especially in MM, is paradigmatic of how the WNT pathway may represent a real communication route between cells of the microenvironment and tumor cells." (PMID 33409156, 2020). "Interestingly, our results indicated that the DKK1 proinvasive effect on HCC cell lines was abrogated in tumor cells lacking TGF-β expression." (PMID 31568519, 2019). "However, the direct effect of recombinant DKK1 on the tumor microenvironment of HCC has not yet been documented." (PMID 31568519, 2019). "Another study showed that the WNT signaling inhibitor Dickkopf 1 (DKK1) is a key factor for this metastatic preference; it reduces the recruitment of macrophages and neutrophils by the WNT/PCP-RAC1-JNK pathway and inhibits the level of tumor-derived TGF-β to inhibit lung metastasis." (PMID 31195692, 2019). "DKK1, a secreted modulator of the Wnt and PI3K/AKT signaling pathways, may contribute to an immunosuppressive tumor microenvironment by influencing Tregs, MDSCs and NK cell functions while also affecting tumor cell NK target expression." (PMID 30400822, 2018). "Besides, the ELISA used in the study of Gobel and as well in the current study does not distinguish between non-tumor and tumor-derived DKK1." (PMID 30227689, 2018). "Thus our data suggest that DKK1 should be further explored as a potential biomarker of cisplatin refractoriness and/or as a target for cisplatin-sensitizing strategies in NSCLC and other tumor types." (PMID 26353782, 2015). "In this case the tumor secreted DKK1 would probably not be observed in the immunohistochemical staining because it is bound to the receptors and might not be accessible by the antibody." (PMID 25048826, 2014). "In a very speculative outline tumor secreted DKK1 might potentially inhibit the WNT pathway in the regional lymph nodes thus inactivating β-catenin and down-regulating the lymph node native DKK1 gene." (PMID 25048826, 2014). "Increased DKK-1 expression was also observed in non-tumour tissue adjacent to the tumour." (PMID 25182503, 2014). "Furthermore, specific DKK1 was predominantly observed to be expressed in HCC tissues but not in the adjacent non-tumor liver tissues." (PMID 24325363, 2013). "Given that DKK1 did not influence tumor cell proliferation or colony formation, then we investigated whether DKK1 regulated HCC cell migration and invasion, which are two of the most important features of malignant cell behavior." (PMID 24325363, 2013). "However, the tumor cells derived from shDKK1-tranfectants showed a much lower level of DKK1 mRNA in comparison with that derived from shControl or nontransfected Bel7402 cells." (PMID 24325363, 2013). "These indicate that DKK1 performs as an oncogenic factor rather than a tumor-suppressor in tumors." (PMID 22649545, 2012). "Since DKK1 itself is a target of TCF/β-catenin mediated transcription, these findings suggest that DKK1 is part of a negative feedback loop in MM and may act as a tumor suppressor." (PMID 22363428, 2012). "Prognostic value of DKK1 in stage II tumor, lymph node negative subgroup." (PMID 22649545, 2012).